RNU6-1039P (RNA, U6 small nuclear 1039, pseudogene)
Gene: Small nuclear RNA gene on chromosome 9 (110,369,592 to 110,369,698, reverse strand). Ensembl gene ENSG00000206658.
Homologues: Orthologues: chimpanzee U6 (100% identical), macaque U6 (96% identical), dog U6 (67% identical), rat LOC120093312 (67% identical), rabbit U6 (66% identical). Paralogues in human: RNU6-125P (87% identical), RNU6-15P (85% identical), RNU6-33P (84% identical), RNU6-468P (84% identical), RNU6-1 (83% identical), RNU6-1060P (83% identical), RNU6-1103P (83% identical), RNU6-116P (83% identical), RNU6-1251P (83% identical), RNU6-19P (83% identical), RNU6-2 (83% identical), RNU6-21P (83% identical), and 1287 more.